GATA3 (GATA binding protein 3)
Diseases named in the same sentence as GATA3 in open-access papers (continued):
Sharing a sentence is not in itself a finding about the gene and the disease.
breast carcinoma (continued). "Apart from the fact that the role of the PPARG/RXRA heterodimer in urothelial cancer is exchanged with the ESR1 hormone receptor in breast cancer, the key transcription factors FOXA1 and GATA3 are downregulated in the basal/SCC-like subtypes of both tumor types." (PMID 26008846, 2015). "Functional genomic annotation using data derived from breast cancer cell-line models indicates that these SNPs localise to putative enhancer elements that bind known drivers of hormone-dependent breast cancer, including ER-α, FOXA1 and GATA-3." (PMID 25652398, 2015). "Tumor cell lines (renal, bladder, prostate and breast cancer) revealed distinct CGI methylation patterns for GATA3 and GATA5 methylation but showed no obvious overall correlation between the epi-alterations." (PMID 24549248, 2014). "The luminal breast cancer cell line MCF7 carries a heterozygous insertion at position 1566, which leads to a frameshift (D336fs) in the second zinc finger and synthesis of a truncated GATA3 protein." (PMID 24758297, 2014). "While markers usually positive in gastric adenocarcinoma such as cytokeratin 20, CDX2, MUC5AC, and Hep Par 1 were negative, those supporting breast carcinoma (estrogen and progesterone receptors, cytokeratin 7, and GATA3) decorated the cancer cells." (PMID 25400965, 2014). "In summary, multiple lines of evidence indicate that GATA3 positively regulates ERα, whereas ERα exerts weak negative regulation on GATA3, resulting in an overall negative feedback in ERα-positive breast cancer cell lines." (PMID 24792166, 2014). "Taken together, these results account for a role of GATA3 as a negative regulator of MPA-induced cell proliferation through prevention of cyclin A2 upregulation, and demonstrate the requirement of GATA3 downregulation for progestin-driven breast cancer growth." (PMID 25479686, 2014). "We then looked at the lncRNAs near ESR1, GATA3, and FOXA1 and analyzed if their expression is only coordinated in luminal breast cancer but not in basal-like breast cancer as the high expression of these genes is characteristic in luminal breast cancer." (PMID 25296969, 2014). "We report here that the expression of the breast luminal differentiation markers estrogen receptor and GATA3 in metastatic ductal breast cancers with a luminal phenotype is not generally lost or decreased upon regional or distant metastasis." (PMID 24205108, 2013). "Finally, we showed that GATA3 (GATA binding protein 3), which co-localizes with TCF7L2 in MCF7 breast cancer cells, is required for recruitment of TCF7L2 to a subset of binding sites." (PMID 22951069, 2012). "Basal A subtype tumors expressed very low level of Gata3, but high levels of E-cadherin and Grhl2, indicating Gata3 was not the essential transcription factor that controls E-cadherin expression in human breast cancers." (PMID 23284647, 2012). "Thus, a network comprising GATA3, FOXA1, ER-alpha and oestrogen constitutes a major proliferation and survival signal for luminal A breast cancer." (PMID 19405945, 2009). "This analysis also confirmed that GATA-3 expression is not an important predictor of breast cancer recurrence in ERα-negative carcinomas (GATA-3-negative vs. GATA-3-positive patients: hazard ratio = 1.46, 95% confidence interval = 0.40 to 5.29; P = 0.559)." (PMID 19549328, 2009). "GATA-3 was neither a predictor for breast cancer disease-free survival nor a prognostic marker, but was shown to be an important and robust luminal differentiation marker, even stronger than FOXA1." (PMID 19549328, 2009). "As FOXA1 may also be a downstream effector of GATA-3, it may be a bridge between GATA-3 and ER pathways, controlling and regulating the biology of luminal mammary cells, breast cancer progression and behaviour." (PMID 19549328, 2009). "The study by Voduc and colleagues found no independent prognostic value of GATA3 in 3,119 breast cancer patients with immunohistochemistry on tissue microarrays." (PMID 19638208, 2009).
breast carcinoma (continued). "Furthermore, mRNA expression of GATA3 and MUC1 correlated positively with breast carcinomas ERα status (r = 0.492, p = 0.004; r = 0.608, p = 0.001, respectively)." (PMID 17078870, 2006). "In addition, we detected a statistically significant correlation in expression between GATA3 and MUC1 genes at the mRNA and protein levels both in normal breast epithelium and in breast carcinomas (p = 0.01)." (PMID 17078870, 2006). "Furthermore, expression of GATA3 and MUC1 genes was analyzed by real-time RT-PCR and immunohistochemistry on breast cancer-specific tissue microarrays." (PMID 17078870, 2006). "It is also apparently a set of breast carcinomas in which there was no direct correlation between levels of GATA3 and MUC1 expression." (PMID 17078870, 2006). "While GATA3, ESR1, PIK3CA, FOXA1, FOXO3, and RB1 protein abundances were not significantly reduced in GATA3mut breast cancers, the expression of genes associated with MDM2 function and phosphorylation of genes associated with ERK signaling and aggressive phenotypes were impacted." (PMID 40439821, 2025). "In hormone receptor-positive tumors, GATA3 modulates cell proliferation through estrogen-responsive genes (e.g., ESR1 and GREB1), while TRPS1 may similarly influence hormonal signaling in breast cancer." (PMID 40969274, 2025). "The variability in GATA3 expression across different subtypes and stages of breast cancer suggests that it may not be universally applicable as a prognostic marker." (PMID 39768217, 2024). "However, the AR-GATA3 interaction does not require ER since AR also recruited GATA3 to loci not occupied by ER, and AR-GATA3 interactions were a feature of ER- breast cancer cells." (PMID 38317241, 2024). "Until recently, TRPS1 has been found to be more specific for breast cancer, reducing the likelihood of misdiagnosis in cases where GATA3 expression might overlap with non-breast malignancies." (PMID 39518009, 2024). "The pioneer factor GATA3 is a well-established ER interacting protein in breast cancer cells that modulates but is not required for ER to bind chromatin, but an interaction between AR and GATA3 has not been previously reported in any tissue or cellular context." (PMID 38317241, 2024). "However, no study had evaluated the prognostic value of GATA-3 protein expression in mammary tumors of female dogs, which are commonly used as animal models in human breast cancer studies." (PMID 37483298, 2023). "Furthermore, the results from our WGCNA analysis indicated the existence of unknown networks between INO80 and a subset of luminal breast cancer biomarkers, including FOXA1, ESR1, GATA3, TFF1, and AR." (PMID 38020889, 2023). "Thus, this GATA3-MGP-TRPS1 panel may need inclusion with Pax-8 and WT-1 to differentiate breast carcinoma from serous carcinoma." (PMID 36284362, 2022). "Expression of GATA3 is absent or significantly reduced in basal-like breast cancers." (PMID 34976209, 2022). "Importantly, 29% (5 of 17) of p18mt;Gata3+/- and none (0 of 8) of p18mt mammary tumors metastasized to the lung, and all lung metastases were positive for mammary basal marker, Ck14." (PMID 34976209, 2022). "We then followed mammary tumors and found that p18-/- tumors were well-differentiated tumors most of which were positive for GATA3 and E-Cad, a downstream target of GATA3, but p18-/- tumors were negative or weakly expressing Vim and EMT-TFs which include TWIST and FRA1." (PMID 34373738, 2021). "Although 29% (5 out of 17) of p18mt;Gata3+/- mammary tumors and none (0 out of 8) of p18mt mammary tumors metastasized to lung, no significant increase of metastasis was observed in p18mt;Gata3+/- tumors relative to p18mt tumors when statistical analysis was conducted." (PMID 34373738, 2021).
breast carcinoma (continued). "Previous studies have indicated that GATA3 was weakly expressed in a wide variety of normal tissues, while its expression was remarkably elevated in breast cancer; moreover, GATA3 has been identified as a novel clinical marker for detecting primary and metastatic breast cancer." (PMID 32850691, 2020). "GATA3, a member of the GATA transcription factor family, plays important roles in regulating breast differentiation and immune system regulation, and with a differ on the prognosis and function on different subtypes of breast cancer, such as basal-like breast cancer and luminal breast cancer." (PMID 32538432, 2020). "Among those, CHEK1 is a checkpoint kinase that is essential for normal and cancer cells, GATA3 is a critical transcription factor with known oncogenic role, and RAD51 has been reported as an oncogene with elevated expression in multiple cancer types including breast cancer." (PMID 31980032, 2020). "Similar results were observed in our study, GATA3, worked as a downstream target of GNAS-AS1/miR-433-3p axis, was identified to promote the M2 polarization of macrophages and enhance the capabilities of proliferation, migration and invasion of ER+ breast cancer cells." (PMID 32538432, 2020). "There was 13% CK7 negative and 28% GATA3 negative tumors in Grade 3 breast cancer." (PMID 31718619, 2019). "In the current study, we analyzed 361 cases of breast cancers (196 cases of Nottingham Grade 3 breast cancers and 159 cases of Grade 1–2 cancers) to delineate the clinicopathologic features of CK7-negative and GATA3-negative tumors and their associations with patient outcome." (PMID 31718619, 2019). "Profiling the CK7 negative and GATA3 negative breast cancers helps to understand the biology of these specific tumor subgroups and may aid in their diagnosis." (PMID 31718619, 2019). "Also, we showed that GATA3 and ENTPD3 were co-expressed in breast cancer at the protein level." (PMID 31754326, 2019). "Interestingly, enforced N3ICD expression results in the upregulation of GATA-3 in breast cancer cell lines with ERα-negative phenotype, while suppressing Notch3 expression downregulates GATA-3 expression in ERα-positive cells." (PMID 30100605, 2018). "Because Ell3 is an additional factor to the triple complex of ER(α), GATA3 and FOXA1 and this complex fine-tunes the expression level of IL-20, it will be essential to assess the clinical meaning of the expression of FOXA1 in combination with the expression of Ell3 in ER(α) breast cancer patients." (PMID 28514748, 2017). "IHC was used to measure the protein expression level of GATA3 in breast cancer tissues in all studies, but each study has its own cut-off value to identify whether the expression level of GATA3 was high or not." (PMID 28394898, 2017). "Since GATA3 and TRPS1 were found to specifically high express in breast cancer among all GATA members, we next performed further exploration on the potential roles of GATA3 and TRPS1 in BC, in connection with other featured biomarkers according to molecular subtypes of breast cancer." (PMID 28423734, 2017). "This suggests that the role of GATA3 may not be as important a transcription factor in MBC compared with female breast cancer, but further validation is required." (PMID 28350011, 2017). "A gene expression signature enriched for genes induced by both estrogen and Gata3 defined a good prognosis subgroup of breast cancer patients, however Gata3-regulated genes were defined as those induced by overexpression of Gata3 in HEK-293 kidney cells, rather than in breast epithelial cells." (PMID 29262572, 2017). "In addition, model systems (e.g., cell lines, animal models) to study GATA3 in breast cancer are lacking, hampering functional studies." (PMID 27588951, 2016).
breast carcinoma (continued). "At this point it is unclear whether that represents the overall poor outcome of non-luminal breast cancers or an active role for GATA3 in suppressing aggressive behavior." (PMID 26097693, 2015). "However, in the luminal breast cancer lines MCF7 and T47D, these genes were induced by GATA3 overexpression, suggesting that upon transformation, GATA3 may change its function to support cancer progression." (PMID 25410484, 2014). "The unique ability of GATA3 as a sole biomarker, that is, not as a part of a genomic signature, to classify breast cancer patients in clinical groups is, thus, uncommon in the context of breast cancer, and suggests that GATA3 is a major force behind processes standing at the core of the disease." (PMID 25410484, 2014). "Since the GDS3283 is a breast cancer data set, we selected the ChIP-seq experiments from breast cancer cell lines (T47D and MCF7 cells) to generate the regulatory TF network with Q < 0.001, which contained five significant TFs: ESR1, GATA3, FOXA1, MYC and E2F1." (PMID 24302579, 2014). "In addition, both parental bipotent and MPCs do not express proteins such as, claudin 3, ER, ESA, MUC1 and GATA3, that are known signature of claudin-low breast cancers." (PMID 22514728, 2012). "The purpose of this study was to explore if the expression of FOXA1 and GATA-3 may provide an opportunity to stratify subsets of patients that could have better outcome, among the ERα-negative/poor prognosis breast cancer group." (PMID 19549328, 2009). "Furthermore, the expression of GATA3 has been shown to correlate with specific breast cancer phenotypes, defined as luminal type A, carrying an improved disease-free survival and overall survival when compared with tumors that do not express GATA3." (PMID 17078870, 2006). "To determine whether GATA3 protein was actively bound to the predicted consensus MUC1 promoter sequence (at -2398/-2393 from the transcriptional start site (TSS)) in vivo and in vitro, we performed ChIP and gel shift analyses in breast cancer cells." (PMID 17078870, 2006). "To determine whether GATA3 is capable of binding the -2398/-2393 sequence in vivo, we performed a chromatin immunoprecipitation (ChIP) assay with nuclear extracts obtained from the MCF7 breast cancer cell line." (PMID 17078870, 2006). "GATA3 is also suggested to induce a growth inhibitory response in triple‐negative breast cancer (TNBC) cell lines, and suppress epithelial‐mesenchymal transition (EMT) in BC." (PMID 41024411, 2025). "Given that of all the breast cancer models investigated, the MDA-MB-453 cell line is the only one in which AR signaling can promote rather than inhibit proliferation, increased or preferential interaction with FOXA1 over GATA3 or other factors may underpin this distinct biology." (PMID 38317241, 2024). "Cooperative promotion of luminal differentiation by AR and GATA3 also mechanistically unites independent studies linking expression of one or the other factor with a more differentiated, less proliferative phenotype in breast cancer cells regardless of molecular sub-type." (PMID 38317241, 2024). "Since GATA3 has been reported to interact with menin in lymphocytes, and menin is known to interact with one member of the FOXA family, FOXA2, we performed immunoprecipitation (IP) and PLA analyses to determine whether menin could interact with GATA3 and FOXA1 in breast cancer cells." (PMID 34561764, 2021).
breast carcinoma (continued). "The identification of only two known or likely breast cancer driver mutations (GATA3 and ERBB3) in two of the specimen was not surprising, as these specimens represent pure PML lacking any invasive component, and thus should bear less genomic resemblance to breast cancer." (PMID 33208147, 2020). "Therefore, whether or not GATA3 mutant breast cancers have better clinical outcomes than ER+ GATA3 wild type tumors, it remains possible that mutant Gata3 or its downstream effectors could be rational targets for breast cancer therapy." (PMID 29262572, 2017). "Positivity for mucicarmine, keratin CAM5.2, CK7, GATA3, BRST-2, mammaglobin, and ER supported a metastatic breast carcinoma to the eyelid without a previously known primary site." (PMID 41342232, 2025). "Immunohistochemistry confirmed positive for cytokeratin 7(CK7), GATA-3 and GCDFP15, as well as negative staining of cytokeratin 20 (CK20), suggesting breast cancer metastasis." (PMID 38500767, 2024). "Although not as strong as the correlation between GATA3 and FOSL1, a positive correlation between GATA3 and FOS mRNA levels was also detected in human breast cancers." (PMID 37353480, 2023). "Gata binding protein 3 (GATA-3), SRY-Box transcription factor 10 (SOX-10), and estrogen receptor (ER) markers were negative, ruling out primary breast cancer." (PMID 37899461, 2023). "Together, these studies indicate that enhancers occupied by ER⍺, FOXA1, and GATA3 frequently also bind GRHL2, but a majority of conserved GRHL2 binding sites in luminal breast cancer cells do not overlap with binding of the ER⍺ signaling complex." (PMID 36691073, 2023). "Our data also show that GATA3 exhibited extremely high sensitivity in 93.4% of ER/PR+ breast carcinomas, while up to 23.0% HER2 + BC and 60.4% TNBC were negative for GATA3." (PMID 36284362, 2022). "Our tumor was positive for CAM 5.2, Syp, ER, PR, and GATA3, and it was negative for HER2, with a Ki-67 index of 21%; therefore, we believe that it was a BNET in the luminal A breast carcinoma category." (PMID 36528621, 2022). "In the clinical breast cancer tissues, IHC staining revealed a consistent expressing pattern in TNBC and statistical analysis showed a negative correlation between GATA3 and MFNG expression in TNBC." (PMID 35804829, 2022). "Immunohistochemical staining of thyroid, which exhibited positive GATA3 and HER2, and negative TTF1, TG, GCDFP15, PR and ER, confirmed breast carcinoma metastases to the thyroid." (PMID 33776925, 2021). "Although not much is known about the relationship between GATA3 and KDM1B, the paralogous KDM1A(LSD1)’s role in luminal breast cancer via GATA3 is well documented." (PMID 33957863, 2021). "Although GATA binding protein 3 (GATA3) and retinoic acid receptor alpha (RARα) were also identified as ERα cooperative factors in breast cancer cells, these were not identified as crucial players in our investigations on ERα-driven SEs." (PMID 32120995, 2020). "All eight cases have been considered as primary breast cancer and pathological diagnoses were made without CK7 and/or GATA3 stains." (PMID 31718619, 2019). "Because both MCF-7 and T-47D are ER+ breast cancer cell lines, and GATA3 and UTX are almost absent in ER- breast cancer MDA-MB-231 cells, we suspected that the interaction between GATA3 and UTX does not depend on ERα." (PMID 31685800, 2019). "This analysis identified 30/229 known cancer genes (T200 targeted platform) and 11/40 TCGA breast cancer genes that were differentially expressed relative to the normal breast cells, including KRAS, GATA3, CCND1, CDH1, GNAS, and several others." (PMID 28794488, 2017). "As morphology and initial IHC evaluation (GATA-3 and ER positivity) could not completely exclude urothelial primary with prostatic duct involvement, morphologic, and IHC comparison of the patient's primary breast cancer and current prostatic neoplasm was necessary." (PMID 27429817, 2016).